NRCAM (neuronal cell adhesion molecule)
Description:
Cell adhesion protein that is required for normal responses to cell-cell contacts in brain and in the peripheral nervous system. Plays a role in neurite outgrowth in response to contactin binding. Plays a role in mediating cell-cell contacts between Schwann cells and axons. Plays a role in the formation and maintenance of the nodes of Ranvier on myelinated axons. Nodes of Ranvier contain clustered sodium channels that are crucial for the saltatory propagation of action potentials along myelinated axons. During development, nodes of Ranvier are formed by the fusion of two heminodes. Required for normal clustering of sodium channels at heminodes; not required for the formation of mature nodes with normal sodium channel clusters. Required, together with GLDN, for maintaining NFASC and sodium channel clusters at mature nodes of Ranvier.
Synonyms: KIAA0343; Bravo; NEDNMS
Tractability: Antibody: its Gene Ontology location is reachable by antibodies, with high confidence; UniProt places it where antibodies can reach, with medium confidence; UniProt predicts a signal peptide or a membrane-spanning region; the Human Protein Atlas places it where antibodies can reach. PROTAC: ubiquitination databases record sites on it; its protein half-life has been measured.
Gene: Protein-coding gene on chromosome 7 (108,147,623 to 108,456,717, reverse strand). Ensembl gene ENSG00000091129.
Subcellular location: Cell membrane; Cell projection, axon; Secreted
Subcellular location (Human Protein Atlas): Nucleoplasm; Cytosol; Plasma membrane; Primary cilium; Vesicles; Predicted to be secreted
Pathways (Reactome):
Developmental Biology: Interaction between L1 and Ankyrins; Neurofascin interactions; NrCAM interactions
Gene Ontology:
Molecular function: ankyrin binding; protein binding; cell-cell adhesion mediator activity
Biological process: angiogenesis; central nervous system development; clustering of voltage-gated sodium channels; axon guidance; axonal fasciculation; axonogenesis; brain development; cell-cell adhesion; neuron migration; positive regulation of neuron differentiation; regulation of axon extension; synapse assembly; synapse organization
Cellular component: cilium; nucleoplasm; axon; axon initial segment; external side of plasma membrane; neuron projection; plasma membrane; extracellular region
Genetic constraint (gnomAD): Loss-of-function variants: 53 observed, 102.24 expected, observed/expected ratio (o/e) 0.52, 90% interval 0.41 to 0.65. The upper end of that interval is the gene's LOEUF score, 0.65, which puts it in group 2 of 6, group 1 being the genes least tolerant of losing a copy. Missense variants: 1,052 observed, 1,259.4 expected, observed/expected ratio (o/e) 0.84, 90% interval 0.79 to 0.88. Synonymous variants: 413 observed, 454.66 expected, observed/expected ratio (o/e) 0.91, 90% interval 0.84 to 0.99.
Homologues: Orthologues: chimpanzee NRCAM (99% identical), macaque NRCAM (99% identical), rat Nrcam (93% identical), rabbit NRCAM (92% identical), pig NRCAM (91% identical), guinea pig NRCAM (91% identical), dog NRCAM (88% identical), mouse Nrcam (85% identical), tropical clawed frog nrcam (72% identical), zebrafish nrcama (61% identical). Paralogues in human: NFASC (45% identical), CHL1 (38% identical), L1CAM (37% identical), CNTN6 (23% identical), CNTN5 (23% identical), CNTN3 (23% identical), CNTN4 (23% identical), CNTN2 (22% identical), CNTN1 (21% identical), ROBO1 (19% identical), ROBO2 (19% identical), PTPRQ (18% identical), and 24 more.
Diseases named in the same sentence as NRCAM in open-access papers:
NRCAM is named in the same sentence as 103 diseases in open-access papers, as found by Europe PMC text mining. Sharing a sentence is not in itself a finding about the gene and the disease. The quoted sentences say what the papers report.
autism (15 papers, 2010 to 2024). Persistent deficits in social interaction and communication and interaction as well as a markedly restricted repertoire of activity and interest as well as repetitive patterns of behavior. "Beyond its development roles, NrCAM has been linked to drug addiction and certain psychiatric disorders, notably autism." (PMID 38241164, 2024). "In the last years, genetic association studies have shown that alterations in NRCAM are associated with psychiatric disorders, such as SZ, autism, and drug addiction." (PMID 32499725, 2020). "Neuron-Glia related cell adhesion molecule (NrCAM) is a candidate autism risk factor that promotes axon guidance through cytoskeletal linkages in developing brain but its role in limbic circuitry has not been investigated." (PMID 30766872, 2019). "This study showed over transmission of particular haplotypes of NrCAM that modulate NrCAM expression in the brain, are associated with a specific subset of autism with a severe obsessive–compulsive behavior." (PMID 24605088, 2014). "Several single nucleotide polymorphisms (SNPs) in the NrCAM gene were also found to be associated with autism further underscoring NrCAM as a strong candidate gene in ASD." (PMID 24605088, 2014). "Although some studies reject NRCAM as an autism candidate, our data suggest a possible link between low mathematical performance and autism risk through NRCAM function, although effects are likely to be small." (PMID 20039944, 2010). "The gene locus of the cell adhesion molecule NrCAM, which regulates fasciculation of mouse brain commissures, shows distinct polymorphisms associated with ASDs, while its knockout in male mice exhibits autism-related behaviors." (PMID 37941606, 2023). "Furthermore, both studies of NrCAM-null mice and genomic association studies have linked NrCAM with impaired sociability, addiction and autism, conditions associated with hypothalamic dysfunction." (PMID 35464310, 2022). "Furthermore, perturbation of NRCAM function can be associated with psychiatry disorders, containing schizophrenia, autism, Alzheimer's disease, mathematics disability and drug addiction." (PMID 26674772, 2015). "In addition to this involvement in brain function, NRCAM has been reported to be associated with autism." (PMID 20039944, 2010). "Previous observations suggest that the NRCAM rs2300043/rs2300045/rs1034825 intron 1 haplotype could be a biomarker for autism." (PMID 36060062, 2022). "Variations in the NrCAM gene have been implicated in autism and schizophrenia, while mutations in the CHL1 (CALL) gene are linked to intellectual disability, schizophrenia, and autism." (PMID 33585481, 2021). "Moreover, male NrCAM knockout mice exhibit autism-related behaviors, including impaired sociability, cognitive rigidity, and repetitive behavior." (PMID 30766872, 2019). "Among the few genes which continued steady rise in placental expression until term, NR3C1 coding for glucocorticoid receptor has been implicated in rheumatism and the malfunction of NRCAM and NEDD9 is related to brain disorders such as autism, Alzheimer’s and Parkinson’s disease." (PMID 23145134, 2012). "Although the intronic SNP implicated here (rs2300052) has not been studied in relation to autism, it is in high LD (r2 > 0.70) with all previously associated NRCAM-tagging SNPs based on HapMap data." (PMID 20039944, 2010). "Similarly, mice with a mutation an autism candidate gene, NrCam, experienced deficiencies in reversal learning but not acquisition learning in a Morris water maze test." (PMID 34663783, 2021).
schizophrenia (12 papers, 2013 to 2026). A major psychotic disorder characterized by abnormalities in the perception or expression of reality. "NrCAM gene polymorphisms are associated with vulnerability to neuropsychiatric disorders such as schizophrenia, as well as vulnerability to substance use disorders." (PMID 41874032, 2026). "The current study adds to this list that NrCAM is linked to a vulnerability to chronic unpredictable stress associated with impaired latent inhibition, a phenotype relevant to acute schizophrenia-like symptoms." (PMID 38601326, 2024). "NrCAM lies at the core of a functional protein network where multiple targets have been associated with schizophrenia." (PMID 38601326, 2024). "NrCAM lies at the core of a functional protein network where multiple targets (including NrCAM itself) have been associated with schizophrenia." (PMID 38601326, 2024). "NrCAM’s functional alterations, and disturbance of interactions with other proteins cause neurodevelopment disorders such as schizophrenia." (PMID 37494308, 2023). "A substantial association has been found between NrCAM and schizophrenia, and it’s a gene among 12 CAM genes that involved in the CAM pathway." (PMID 37494308, 2023). "Of those, NRCAM, the neural cell adhesion molecule gene has a well-established association with schizophrenia." (PMID 23391219, 2013). "Moreover, earlier findings have linked NRCAM (data of GWAS) to schizophrenia." (PMID 36060062, 2022). "This could be of relevance in neuropsychiatric disorders, such as autism spectrum disorders (ASD) and schizophrenia, to which NrCAM is linked and where neurite outgrowth and branching may be down‐regulated by NrCAM shedding in a process impairing neuronal connectivity." (PMID 30833305, 2019). "Here we investigated the effects of chronic unpredictable stress on latent inhibition, a measure of selective attention and learning which shows alterations in schizophrenia, in NrCAM knockout (KO) mice and their wild-type littermate controls (WT)." (PMID 38601326, 2024).
Alzheimer disease (5 papers, 2015 to 2025). A progressive, neurodegenerative disease characterized by loss of function and death of nerve cells in several areas of the brain leading to loss of cognitive function such as memory and language. "Increased NRCAM levels have been reported in the blood plasma of patients diagnosed major depressive disorder, and the function of NRCAM has been associated with Alzheimer's disease." (PMID 34870700, 2021). "NRCAM has already been found functioning in multiple diseases, such as liver cancer, Alzheimer’s disease, thyroid carcinoma and so on69–71." (PMID 41023110, 2025). "Previous studies have determined the role of CNTN1 in neurogenesis, Alzheimer’s disease, multiple sclerosis, and chronic inflammatory demyelinating polyneuropathy as a neuronal cell adhesion molecule and a component of septate-like junctions between the terminal myelin loops and axolemma." (PMID 33194679, 2020).
melanoma (5 papers, 2007 to 2022). A malignant, usually aggressive tumor composed of atypical, neoplastic melanocytes. "It has been reported that NrCAM plays oncogenic effects in the development, migration, and invasion of the colon, pancreas, brain cancer, and melanoma." (PMID 35388173, 2022). "Meanwhile, HLA-DRA, INHBA, DKK1, CTGF, PMP22, FLRT3 and NRCAM genes, upregulated in G10, were described as overexpressed in invasive melanomas." (PMID 27206673, 2016). "Previous studies have shown that NrCAM is a target gene of β-catenin signalling in human melanoma, and colon carcinoma cell lines and tissues." (PMID 17667921, 2007). "The induction of NrCAM transcription by β- or γ-catenin plays a role in melanoma and colon carcinogenesis, most likely by promoting cell growth and motility." (PMID 17667921, 2007). "Similarly, genes related to melanoma invasion were downregulated in SIRT2-deficient melanoma cell lines (e.g., HLA-DRA, IL-6, CD74, and HLA-DRB1 in the SSW30 clone, Dataset S1; PTPRZ1, FST, and NRCAM in the SSM15 clone, Dataset S2)." (PMID 31091806, 2019). "Moreover, suppression of NrCAM expression by siRNA in melanoma cells inhibited the adhesive and tumourigenic ability of these cells." (PMID 17667921, 2007). "In addition to the nervous system, expression of the NrCAM gene (chromosome 7q31.1–q31.2) has also been demonstrated in a variety of healthy or neoplastic tissues and cell lines including pancreatic cancer, melanoma, renal and colon carcinoma, adrenal gland, placenta, thyroid, and testis." (PMID 17667921, 2007).
neuroblastoma (5 papers, 2019 to 2025). Neuroblastoma (NB) is the most common solid, extracranial childhood tumor. "In contrast, an increased expression of NrCAM and L1 in gene array analyses has been associated with a favorable outcome in pediatric neuroblastoma." (PMID 31989042, 2019). "Accordingly, an increased NrCAM gene detection has been reported for low risk neuroblastomas with favorable outcome before." (PMID 31989042, 2019). "We hypothesized that the expression of the NRCAM alternative isoform (Q92823-4) is likely neuroblastoma-associated and, thus, specific to the SH-SY5Y cell line." (PMID 36499391, 2022). "CHL1 and NrCAM expression was associated with low-grade pediatric neuroblastoma." (PMID 31989042, 2019). "NrCAM expression as well as clinical, pathologic and molecular characteristics of the analysed neuroblastoma tissue samples." (PMID 31989042, 2019). "In the present study, the protein expression of CHL1 and NrCAM in pediatric neuroblastoma in correlation to clinical and survival data were analyzed." (PMID 31989042, 2019). "We therefore studied the expression of CHL1 and NrCAM according to the course of disease in children with neuroblastoma." (PMID 31989042, 2019). "CHL1 and NrCAM expression levels were histologically assessed by tissue microarrays from surgically resected neuroblastoma specimens of 56 children." (PMID 31989042, 2019). "We therefore determined the expression of CHL1 and NrCAM by immunohistochemistry in a neuroblastoma tissue microarray and correlated it to the individual course of disease." (PMID 31989042, 2019). "Expression of CHL1 as well as NrCAM has already been studied in neuroblastoma before." (PMID 31989042, 2019). "CHL1 was expressed in 9% and NrCAM in 51% of neuroblastoma tissue samples." (PMID 31989042, 2019). "Further validation of the NRCAM alternative isoform protein in neuroblastoma patient samples as well as research on NRCAM-specific ligands and antibodies that trigger internalization will further strengthen the case for alternative NRCAM as a delivery target for neuroblastoma." (PMID 36499391, 2022). "Validation of these isoforms using surface proteomics confirms a SH-SY5Y-specific alternative NRCAM (neuron-glia related cell adhesion molecule) isoform, which is absent in typical brain neurons, but present in neuroblastomas, making it a receptor of interest for neuroblastoma-specific therapeutics." (PMID 36499391, 2022). "Meanwhile, three independent neuroblastoma cohorts (Kocak, SEQC, TARGET) consistently revealed significantly elevated expression of NRCAM, VSTM2L, SLIT3, and ALCAM in Stage 4S tumors." (PMID 40448172, 2025). "Hence, alternatively spliced NRCAM isoforms may present a novel opportunity for targeting neuroblastoma cells using, for example, receptor-targeted nanoparticles containing cancer suppressor miR-186, which has been shown to inhibit tumor growth and immune escape in neuroblastoma." (PMID 36499391, 2022). "Taken together, these results show that neuroblastoma cells express alternatively spliced NRCAM which is likely not expressed in the normal human brain." (PMID 36499391, 2022).
thyroid cancer (5 papers, 2019 to 2025). "In thyroid cancer, depletion of neuronal cell adhesion molecule (NrCAM) markedly impaired tumor growth and tumorigenic potential, and high-affinity NrCAM antibodies may offer a novel therapeutic option for NrCAM-positive malignancies." (PMID 41163091, 2025). "The protein complex also contains α4β1 integrins, which most likely bind to the third Fn-like domain of NrCAM since antibodies against this domain suppress the MAPK and Akt signaling pathways in thyroid cancer FTC133 cells." (PMID 39594667, 2024). "In thyroid cancer K1 cells, EGFR co-immunoprecipitates with neural glia-related cell adhesion molecule (NrCAM), also a member of the L1CAM family." (PMID 39594667, 2024). "Proteolytic cleavage of NrCAM at the cell surface of K1 cells results in the release of the extracellular domain of NrCAM, which activates EGFR signaling when presented in the culture medium to thyroid cancer IHH4 cells, suggesting that it binds in trans to EGFR at the cell surface." (PMID 39594667, 2024).
autism spectrum disorder (4 papers, 2018 to 2024). A spectrum of developmental disorders that includes autism, and Asperger syndrome. "The neuronal cell adhesion molecule contactin-4 (CNTN4) is genetically associated with autism spectrum disorder (ASD) and other psychiatric disorders." (PMID 38745463, 2024). "NrCAM is notable as a potential target for mutation in neurodevelopmental disease, as polymorphisms in the NrCAM locus have been associated with autism spectrum disorders (ASD)." (PMID 30766872, 2019).
colon carcinoma (4 papers, 2007 to 2022). "Among them, NRCAM, the cell surface glycoprotein, has been reported to be significantly associated with nodal and distant metastasis in colon cancer." (PMID 32054830, 2020). "In contrast, higher levels of NrCAM in tumorous tissue deriving from glioblastoma, pancreatic, and colon cancer as well as papillary thyroid carcinoma were associated with a poorer prognosis." (PMID 31989042, 2019). "Alterations in the expression and function of CAMs, especially L1, CHL1 and NrCAM, have been associated with pathological processes leading to different malignancies including melanoma, prostate and colon cancer." (PMID 31989042, 2019).
glioblastoma (4 papers, 2018 to 2025). The most malignant astrocytic tumor (WHO grade IV). "Chromosome 7 is usually disrupted in many cancers, here we detected the amplification of several genes already implicated in glioblastoma such as: EGFR, SEPT14, NAMPT, NRCAM, AAS and PTPRZ1." (PMID 29844869, 2018).
glioma (4 papers, 2007 to 2023). A benign or malignant brain and spinal cord tumor that arises from glial cells (astrocytes, oligodendrocytes, ependymal cells). "The most notable lncRNA is LINC00599, which has DBSs in many NGS genes in most gliomas, including GABBR1, NRCAM, PTPRS, GLRB, GRIA4, GRIK3, and MAP2, and the most notable NGS gene is MAP2, which is associated with microtube assembly and regulated by multiple lncRNAs through the same DBS." (PMID 37693314, 2023).
papillary thyroid carcinoma (3 papers, 2007 to 2020). "Thus, the induction and upregulation of NrCAM expression could be implicated in the pathogenesis and behaviour of papillary thyroid cancers." (PMID 17667921, 2007). "NrCAM is upregulated in a series of carcinomas like papillary thyroid carcinomas and significant overexpression of the NrCAM in SCLC was also noted in comparison to normal lungs." (PMID 33255394, 2020). "In the present study, NrCAM expression was analysed in a series of papillary thyroid carcinomas (PTCs) and paired normal tissues (NT)." (PMID 17667921, 2007). "At present, there is no information concerning the expression of NrCAM (gene or protein), its cellular localisation and distribution, or its role in the evolution of thyroid papillary carcinomas." (PMID 17667921, 2007). "We did observe that tumours with more aggressive clinical behaviour (eg, pT4N1) tended to express higher levels of NrCAM, suggesting possible involvement of this molecule in regional spread – a characteristic feature of papillary carcinomas – but these differences were not statistically significant." (PMID 17667921, 2007).